SCN4A (sodium voltage-gated channel alpha subunit 4)
Diseases named in the same sentence as SCN4A in open-access papers (continued):
Sharing a sentence is not in itself a finding about the gene and the disease.
congenital myopathy (21 papers, 2017 to 2025). "To date, several cases of compound heterozygous or homozygous SCN4A variants, exhibiting null and/or loss-of-function, have been reported in congenital myopathy, congenital myasthenic syndrome, or fetal dyskinesia." (PMID 39164360, 2025). "More recently, homozygous or compound heterozygous variants of SCN4A have been reported as causes of congenital myopathy, fetal hypokinesia, and fetal death, with autosomal recessive inheritance." (PMID 39164360, 2025). "More recently, LOF variants were also found in patients with a new form of SCN4A-related congenital myopathy named severe fetal congenital myopathy 22B, (OMIM #603967)." (PMID 38255008, 2024). "We have reported undocumented phenotypic features associated with SCN2A and SCN4A variants and two novel variants linked to severe fetal congenital myopathy 22B." (PMID 38255008, 2024). "We report a Han Chinese patient presented with congenital myopathy with two missense SCN4A variants." (PMID 38187266, 2023). "More recently, loss-of-function variants in the SCN4A gene were also noted to be associated with rarer, autosomal recessive forms of congenital myasthenic syndrome and congenital myopathy." (PMID 38187266, 2023). "Further investigations are required to understand the mechanism of fatigue in CMS/congenital myopathy caused by mutations in SCN4A." (PMID 35670010, 2022). "These cases are distinctly different, however, from the recently described syndrome of congenital myopathy with severe fetal hypokinesia caused by biallelic mutations for SCN4A." (PMID 32117035, 2020). "Recently, homozygous mutations in the SCN4A gene were described to cause severe congenital myopathy." (PMID 32411069, 2020). "More recently, biallelic mutations in SCN4A have been reported in congenital myasthenic syndromes, at times with myopathy, and in severe congenital myopathy with fetal hypokinesia." (PMID 32117035, 2020). "Conversely, in the series of 6 families with congenital myopathy associated with SCN4A recessive mutations, 1 of 4 available surviving patients had a 60% CMAP decrement with 10 Hz stimulation." (PMID 30824560, 2019). "Further investigations are required to understand the mechanism for the fatigue in CMS/congenital myopathy caused by mutations in SCN4A." (PMID 30824560, 2019). "Our report is the third case of a homozygous recessive mutation in SCN4A found in CMS/congenital myopathy, and all 3 missense mutations are at arginine residues in the S4 segment of the domain IV voltage sensor (p.R1454W6, p.R1457H7, and p.R1460W)." (PMID 30824560, 2019). "Several patients with recessive mutations in SCN4A were diagnosed with CMS/congenital myopathy." (PMID 35670010, 2022). "Recessive loss of function homozygous or compound heterozygous variants in SCN4A, which encodes sodium voltage-gated channel, alpha subunit 4, have been reported to cause a spectrum of disease ranging from severe fetal hypokinesia to a ‘classical’ congenital myopathy." (PMID 33827624, 2021). "These last 5 years, SCN4A mutations inducing Nav1.4 loss of function (LoF) were identified as the cause of dominantly and recessively-inherited disorders with muscle weakness: periodic paralyses with hypokalemic attacks, congenital myasthenic syndromes and congenital myopathies." (PMID 34671263, 2021). "A small cohort study presented a few patients with severe fetal congenital myopathy 22B carrying homozygous and compound heterozygous LOF variants in SCN4A." (PMID 38255008, 2024). "We present a now 18-year-old female patient with a severe congenital myopathy phenotype, originally diagnosed as mitochondrial myopathy, however later revealed to constitute a SCN4A-related myopathy based on genetic testing." (PMID 36090556, 2022). "The clinical features of SCN4A-related congenital myopathy and myasthenic syndrome were reviewed." (PMID 38187266, 2023).
congenital myopathy (continued). "In our view, however, neither a single allelic variant of SCN4A nor a dominant inheritance pattern has been associated with a syndrome for which congenital myopathy is the predominant feature." (PMID 32117035, 2020).
myotonia congenita (11 papers, 2009 to 2025). "The most common entity identified in patients was myotonia congenita with variants in the SCN4A and CLCN1 genes." (PMID 38758368, 2024). "In another pedigree, the association of a lone F167L variant with myotonia congenita was uncertain as it was identified together with a known pathogenic SCN4A variant." (PMID 34529042, 2022). "Myotonia congenita caused by SCN4A mutations was diagnosed in 3 individuals." (PMID 38758368, 2024). "The NDMs are comprised of myotonia congenita (MC) due to mutations in the skeletal muscle chloride channel gene CLCN1 encoding CLC-1 as well as paramyotonia congenita (PMC) and sodium channel myotonia (SCM) caused by mutations in the skeletal muscle sodium channel gene SCN4A encoding Nav1.4." (PMID 32848354, 2020). "While our patient with a deletion within SCN4A lacked symptoms of myotonia congenita, it is possible that the deletion leads to mild muscular symptoms and thereby to reduced bone strength." (PMID 30042735, 2018).
Hypokalemia (7 papers, 2018 to 2025). An abnormally decreased potassium concentration in the blood. "We identified a reported homozygous SCN4A mutation (c.4352G > T p.Arg1451Leu) in a teenage boy with hypokalemia." (PMID 31068157, 2019).
sudden infant death syndrome (7 papers, 2009 to 2021). Unexpected death in infancy which remains unexplained following autopsy, review of the medical history, and investigation of the death circumstances and death scene. "We have recently identified similar SCN4A mutations in association with sudden infant death syndrome." (PMID 31440732, 2019). "Indeed, it has been recently highlighted that SCN4A variants may determine relevant symptoms in neonates, compromising respiratory and laryngeal function, and might be associated with Sudden Infant Death Syndrome." (PMID 32655465, 2020).
epilepsy (6 papers, 2019 to 2023). A brain disorder characterized by episodes of abnormally increased neuronal discharge resulting in transient episodes of sensory or motor neurological dysfunction, or psychic dysfunction. "In a family with epilepsy and ET, a disease-segregating mutation p.(Gly1537Ser) in the SCN4A gene was identified and functional analyses demonstrated more rapid channel kinetics and altered ion selectivity, which may contribute to the phenotype of tremor and epilepsy in this family." (PMID 31404076, 2019). "We propose that the SCN4A mutation contributed to the apneas in our case, irrespective of the underlying cause of the epilepsy." (PMID 31440732, 2019). "Apnea and cyanosis can be an independent consequence of seizures, and we cannot definitively state that the SCN4A mutation in this case caused laryngospasm and contributed to the episodic apnea, and we do not suggest that the SCN4A mutation was the cause of the proband's epilepsy per se." (PMID 31440732, 2019).
cardiac arrhythmia (5 papers, 2020 to 2022). Any disturbances of the normal rhythmic beating of the heart or MYOCARDIAL CONTRACTION. "The tissue-specific expression of SCN4A most probably explains why Nav1.4 dysfunction only impacts skeletal muscles even if anecdotic reports of cardiac arrhythmia in individuals with dominant SCN4A mutations have been published." (PMID 34671263, 2021). "Scn4a and Scn4b mutations and expression changes have been shown to be associated with arrhythmia and tightly regulated expression of these channels is required for physiological conduction." (PMID 32179820, 2020). "Extra-muscular manifestations are thought to be non-typical for NDM patients, even though the role of SCN4A variants in causing cardiac arrhythmias and Brugada syndrome remains debated." (PMID 33263785, 2021). "In our cohort, no patient with SCN4A mutations presented relevant cardiac involvement; on the other hand, six NDM-CLCN1 patients had cardiac arrhythmias or conduction defects, requiring the implantation of a pacemaker in three patients." (PMID 33263785, 2021).
myotonic disorder (5 papers, 2016 to 2022). "Whole‐exome sequencing identified a known pathogenic mutation in the SCN4A gene that has been reported in several unrelated families with myotonic disorder." (PMID 31440732, 2019). "Concerning myotonic dystrophies, the co-segregation of DM2 mutation with mutations in CLCN1 or SCN4A genes were linked to unusual clinical findings." (PMID 30038349, 2018).
Brugada syndrome (4 papers, 2020 to 2022). A genetically heterogeneous condition characterized by complete or incomplete right bundle branch block accompanied by ST elevation in leads V1-V3. "Interestingly, variants in SCN4A have also been reported in patients with clinical diagnosis of Brugada syndrome, a primary arrhythmia syndrome." (PMID 33789662, 2021). "In a recent report, a p.G1306E mutation of SCN4A gene caused NDM and Brugada syndrome after treated with flecainide." (PMID 32276507, 2020).
Myalgia (3 papers, 2017 to 2022). "Some SCN4A mutations are known to be associated with myalgia (e.g., c.1333G>A, c.3917G>C, c.3466G>A), in our patients only 6/22 showed either c.1333G>A or the c.3917G>C mutation, thus explaining only a minority of myalgic patients." (PMID 33263785, 2021).
Tremor (3 papers, 2019 to 2020). An unintentional, oscillating to-and-fro muscle movement about a joint axis. "The essential tremors and chronic seizures found in the family members with a p.G1537S mutation in the SCN4A gene may also have been attributable to the disturbance of the resurgent Na+ currents in the Nav1.4 channel." (PMID 32276507, 2020).
breast carcinoma (2 papers, 2018 to 2020). "Enhanced protein expression in a VGSC group, such as SCN5A in human breast cancer and SCN4A in prostate cancer, was reported to be associated with cancer invasiveness." (PMID 30001383, 2018).
congenital myotonia (2 papers, 2020 to 2023). Myotonia congenita (MC) is a genetic neuromuscular channelopathy which usually presents in early childhood resulting in a delay of skeletal muscle relaxation following contraction. "The other case of congenital myotonia with joint abnormalities (SCN4A p.N1180I) also had signs of neonatal myopathic weakness with polyhydramnios, high arched palate, and downslanting palpebral fissures." (PMID 32117035, 2020).
hydrops (2 papers, 2022 to 2025). "For variants in genes critical to excitation-contraction coupling (CACNA1S, SCN4A, STAC3), oedema may present as early as 15–18 w, simultaneously accompanied by arthrogryposis." (PMID 36761691, 2022).
hyperkyphosis (2 papers, 2016 to 2019). "Hyperlordosis or hyperkyphosis were reported in patients carrying SCN4A, RAPSN, or SYB1 mutations." (PMID 30808424, 2019).
myotonic dystrophy type 2 (2 papers, 2017 to 2018). Myotonic dystrophy type 2 (MD2), also known as proximal myotonic myopathy, is a very rare genetic multi-system disorder of late childhood or adult-onset characterized by mild myotonia, muscle weakness, and rarely cardiac conduction disorders. "The symptoms of milder SCN4A mutations may be confused with other similar myalgic syndromes, including fibromyalgia and myotonic dystrophy type 2." (PMID 28330959, 2017).
ptosis (2 papers, 2019). The drooping of the upper eyelid. "The father who carried the nonsense SCN4A mutation found in the proband possibly had mild fixed ptosis but was otherwise healthy." (PMID 30824560, 2019).
rhabdomyolysis (2 papers, 2022 to 2025). Necrosis or disintegration of skeletal muscle often followed by myoglobinuria. "In particular, the upregulation of SCN4A, a voltage-gated sodium channel, in simvastatin-treated cells may strengthen the inward-facing sodium current and exacerbate decreased serum potassium levels, thus increasing hypokalemic periodic muscle paralysis and rhabdomyolysis risk." (PMID 40149400, 2025).
rhabdomyosarcoma (2 papers, 2019 to 2022). A rare aggressive malignant mesenchymal neoplasm arising from skeletal muscle. "Surprisingly, no SCN4A gene transcription for the skeletal muscle NaV1.4 was detected as one would expect for a rhabdomyosarcoma cell line." (PMID 35413129, 2022). "Of these genes, several may be important for rhabdomyosarcoma, including a homeobox transcription factor (PROX1), a tumor suppressor (CD82), a transposable element (PDBD5), a muscle sodium channel (SCN4A), and a long intergenic non-coding RNA (LINC00689) (see Discussion)." (PMID 31480361, 2019).
thyrotoxicosis (2 papers, 2023 to 2025). A hypermetabolic syndrome caused by the elevation of thyroid hormone levels in the serum. "Autosomal dominant channelopathies (for example, CACNA1S, SCN4A) in many families; no biochemical thyrotoxicosis; similar triggers but earlier age of onset and strong family history." (PMID 41523487, 2025).
amyotrophic lateral sclerosis (1 paper, 2020). Amyotrophic lateral sclerosis (ALS) is a neurodegenerative disease characterized by progressive muscular paralysis reflecting degeneration of motor neurons in the primary motor cortex, corticospinal tracts, brainstem and spinal cord. "Sodium channel blockers are known to be effective for muscle stiffness in patients with a mutation in the SCN4A gene encoding Nav1.4 and for muscle cramps in amyotrophic lateral sclerosis (ALS) patients." (PMID 32368413, 2020).
cardiac hypertrophy (1 paper, 2020). "As a main result we found that AGAT−/− mice exhibited altered gene expression related to energy metabolism (Fbp2, Ucp2), cardiac hypertrophy and fibrosis (Nppa, Ctgf), immune response (Fgl2), and the conduction system of the heart (Dsc2, Ehd4, Hcn2, Hcn4, Scn4a, Scn4b)." (PMID 32179820, 2020).
Cerebral atrophy (1 paper, 2019). Atrophy (wasting, decrease in size of cells or tissue) affecting the cerebrum. "Mild cerebral atrophy was reported in SCN4A-related CMS and in ALG14-related CMS." (PMID 30808424, 2019).
Cognitive impairment (1 paper, 2019). Abnormal cognition is characterized by deficits in thinking, reasoning, or remembering. "Mild to severe cognitive impairment has been reported in patients carrying mutations in the SLC5A7 gene, DPAGT1 gene, SNAP25 gene, COL13A1 gene, MYO9A gene, MUNC13–1 gene, and in SCN4A-related CMS." (PMID 30808424, 2019).
colon cancer (1 paper, 2022). "However, we also found other Nav-encoding genes being importantly expressed in colon cancer cells, such as SCN4A which is significantly expressed in HT29 cells." (PMID 36612049, 2022). "We have also found that the SCN4A and SCN8A subunits are expressed at significant levels, but their role in colon cancer cell properties such as invasive capacities are not yet identified." (PMID 36612049, 2022).
Dravet syndrome (1 paper, 2021).
hepatocellular carcinoma (1 paper, 2022). A malignant tumor that arises from hepatocytes. "SCN4A is the fourth member of the SCN family that encodes sodium channels, is highly expressed in hepatocellular carcinoma, and has varying degrees of correlation with tumor grade, lymph node metastasis status, and cancer stage." (PMID 36389709, 2022).
hyperthyroidism (1 paper, 2023). Overactivity of the thyroid gland resulting in overproduction of thyroid hormone and increased metabolic rate. "It is a rare case of SCN4A p.R1135H gene variant combined with hyperthyroidism resulting in HPP with respiratory muscle paralysis to raise awareness of the disease and avoid misdiagnosis and missed diagnosis." (PMID 36733446, 2023).
respiratory failure (1 paper, 2022). The significant impairment of gas exchange within the lungs resulting in hypoxia, hypercarbia, or both, to the extent that organ tissue perfusion is severely compromised. "Impaired contraction of skeletal respiratory muscles, thought to contribute to respiratory failure in SIDS, is caused by variants in the voltage-gated sodium channel NaV1.4, which is encoded by the SCN4A gene." (PMID 36135215, 2022).
scoliosis (1 paper, 2020). A congenital or acquired spinal deformity characterized by lateral curvature of the spine. "Severe scoliosis with peripheral contractures in childhood was described for siblings with myotonic stiffness, profuse myotonic discharges, and the SCN4A p.P1158A mutation, but no details were provided about the clinical presentation at birth." (PMID 32117035, 2020).
Vertigo (1 paper, 2024). An abnormal sensation of spinning while the body is actually stationary. "Mutations in ion channel genes (HyperPP: SCN4A, HypoPP: SCN4A/CACNA1S) are the main cause of both diseases, and acetazolamide can reduce vertigo attacks to some extent in MD; hence, MD may be related to ion channel-related dysfunction." (PMID 39429303, 2024).
myopathy (10 papers, 2017 to 2025). A disease of the muscle in which the muscle fibers do not function properly. "The patient's phenotype is in line with the few published cases of autosomal recessive SCN4A-related myopathy." (PMID 36090556, 2022). "For SCN4A, the clinical spectrum of myopathies is well known." (PMID 36877742, 2023). "Mutations in the transient sodium channel Nav1.4 alpha subunit (SCN4A) gene underlie a diverse group of dominantly inherited nondystrophic myotonias that run the spectrum from subclinical myopathy to severe muscle stiffness, disabling weakness, or frank episodes of paralysis." (PMID 34996390, 2022).
cancer (9 papers, 2015 to 2024). A tumor composed of atypical neoplastic, often pleomorphic cells that invade other tissues. "Therefore, based on these results, we suggested that GABRA3, SLC6A3, GABRQ, and SCN4A might be cancer-specific targets of Carvacrol which were further screened in the subsequent study." (PMID 35401884, 2022). "SCN4A was sodium channel genes that might also affect cancer cells." (PMID 35401884, 2022). "No studies to date have investigated the potential connections between these gene-cancer pairs, therefore, SCN3A-LGG, SCN3B-LGG, SCN4A-KIRC, and SCN1B-PAAD would be potential clinically significant research topics for future study." (PMID 39060933, 2024). "Among these gene-cancer pairs, SCN3A-LGG, SCN3B-LGG, SCN4A-KIRC, SCN1B-UVM, and SCN1B-PAAD have a relatively high gene expression level, and have a relatively large case number except for UVM (n = 79)." (PMID 39060933, 2024). "Results showed that GABRA3, SLC6A3, GABRQ, SCN4A, and GABRG3 were overexpressed in cancer compared with normal liver tissues." (PMID 35401884, 2022). "The mRNA expression of SCN4A and SCN7A in 38 types of cancers was detected and compared with that in normal tissues." (PMID 35126466, 2021). "The expression of SCN4A was highly in several cancers, such as LIHC; however, its expression was lowly expressed in some other types of cancer tissues, such as BRCA and HNSC." (PMID 35126466, 2021). "Results showed that expressions of DRD1, GABRA3, SLC6A3, GABRQ, and SCN4A in cancer were significantly higher than those in noncancer tissues." (PMID 35401884, 2022). "The role of SYT2, SCN4A, GPR37, and F2 in cancers has not been well studied." (PMID 36110953, 2022).
skeletal muscle disorder (5 papers, 2014 to 2025). A disease involving the skeletal muscle tissue. "Mutations in SCN4A gene encoding NaV1.4 causes skeletal muscle disorders in humans." (PMID 40273189, 2025).